STMN1 (stathmin 1)
Diseases named in the same sentence as STMN1 in open-access papers (continued):
Sharing a sentence is not in itself a finding about the gene and the disease.
tumor (continued). "In TGGA data analysis, we found that the expression of STMN1 in tumor tissues is also higher than that in adjacent tissues, which indicated that the oncogenic roles of STMN1 not only depends on post-transcriptional regulation, but also depends on the mRNA level." (PMID 33526768, 2021). "Taken together, these findings indicate that STMN1 tends to function as a metastatic suppressor in stem-like tumor cells and suggest that understanding the stemness profiles and numbers of stem-like cells in cancer patients are crucial for utilizing STMN1 as a therapeutic target." (PMID 33921319, 2021). "Tumor-associated macrophages (TAM) can also take up miR-770 from TNBC tumor cells, and further analysis revealed that miR-770 negatively regulates gene coding for Stathmin 1 (STMN1)." (PMID 32967267, 2020). "MAX, DCAF7, and STMN1 were identified as novel targets of miR-193a that could contribute to its tumor-suppressive effect." (PMID 32410663, 2020). "We implanted parental and STMN1 knockout P3 GBM cells intracranially in immunodeficient mice that were fed a DOX diet and monitored tumor growth by daily weighing until a 8–10% loss was observed at which point animals were randomly enrolled in control or VB treatment cohorts." (PMID 30082792, 2018). "In our study, we proved that miR-770, a potential tumor suppressor, could specifically target and down-regulate STMN1, thus inhibit the metastasis and chemo-resistance of TNBC cells." (PMID 29323124, 2018). "Moreover, cell growth was inhibited by STMN1 depletion as well as T3 treatment, confirming that T3 plays a role in suppression of tumor growth." (PMID 27934948, 2016). "Specific knockdown of STMN1 suppressed cell proliferation and xenograft tumor growth in mice." (PMID 27934948, 2016). "Notably, THRA and THRB mRNA expression were decreased, whereas expression of STMN1 was enhanced, in tumor specimens." (PMID 27934948, 2016). "Stathmin 1 (STMN1) is a biomarker in several types of neoplasms." (PMID 27270953, 2016). "Notably, tumor growth was largely reduced in regions containing STMN1-knockdown cells, but was maintained in regions containing shLuc control cells (n = 4), suggesting that STMN1 is crucial for tumor cell growth." (PMID 27934948, 2016). "In solid tumors, high Stathmin 1 expression correlates with tumor growth and progression." (PMID 26356819, 2015). "Phosphorylation at either Ser16 or Ser63 strongly reduces or abolishes the ability of STMN1 to bind to and sequester soluble tubulin, while phosphorylation at Ser38 may be a novel biomarker of increased tumor cell proliferation and impaired prognosis." (PMID 26087399, 2015). "In addition, STMN1, as an oncoprotein, is involved in tumour metastasis, cell invasion and migration and is a considered therapeutic cancer target." (PMID 25928257, 2015). "The STMN1 protein expression was mainly localized in the cytoplasm of the tumor cells." (PMID 22470493, 2012). "Together, these diverse differences imply that STMN1 phosphorylation and activities are cell type- and growth factor-specific and that cancer-specific approaches will likely be required to effectively block STMN1 phosphorylation-mediated tumor cell growth and metastasis." (PMID 40723207, 2025). "In vivo studies also suggest that overexpression of ExomiR-770 directly targets STMN1, a stathmin family phosphoprotein involved in intracellular signaling, thereby increasing doxorubicin sensitivity via inducing apoptosis and decreasing the tumour volume and metastasis and." (PMID 38455764, 2024). "Notably, STMN1 was an essential component member of the turquoise module (r = 0.67, p = 4.17e-49), which further proved the existence of a special correlation between STMN1 up-regulation and tumor vascular invasion in HCC patients." (PMID 35210426, 2022).
tumor (continued). "Tumour-derived EVs were enriched in stathmin-1 compared with those from immortalized normal squamous oesophagus epithelial cell line (Het-1A), indicating that EV stathmin-1 content may be considered a surrogate of its intracellular levels, and therefore, a suitable tumour biomarker." (PMID 34205183, 2021). "We surmise whether PIWIL1 promotes tumor cell proliferation and invasion via STMN1." (PMID 26317901, 2015). "Conversely, the second niche, identified primarily in patients who did not respond to mono-immunotherapy, is distinguished by the proliferation of STMN1+ cECs and a significant accumulation of MYF5+ MSCs at the invasive frontiers of the tumor." (PMID 40107247, 2025). "The results indicated upregulation of STMN1 in NSCLC, which distinguished tumor tissue from normal tissue." (PMID 40013670, 2025). "Our human tumor specimen study revealed correlations between CIC structures, poor adenocarcinoma differentiation, low STMN1 expression, and poor patient prognosis, indicating the clinical relevance of our current study." (PMID 40225568, 2025). "Although PTX/si@MPDA-PEG has exhibited excellent anti-tumor efficacy, the specific mechanism between PTX and STMN1 remains elusive and warrants further in-depth exploration." (PMID 41361792, 2025). "SELP+ HEVs and APOD+ myCAFs foster favorable immunomodulatory stromal niches for improved outcomes, while STMN1+ cECs and MYF5+ MSCs form immunosuppressive niches in tumor invasion regions, highlighting therapeutic targets." (PMID 40107247, 2025). "Consistently, the mRNA and protein levels of TUBB3, STMN1, and TAU were dramatically reduced in the tumour tissues of the RNF31 knockdown and IPO13 knockdown groups treated with PTX." (PMID 39915011, 2025). "The B-STMN1 subtype highly expressed the proliferation-related gene STMN1, suggesting that there is a subtype of proliferating B cells in the TME of MIBC that affects tumor immunity." (PMID 38216927, 2024). "Differential expression analysis of TCGA-LIHC tumor tissues and adjacent normal tissues revealed that the expression differences of TMEM45A, S100A10, SERPINA12, BHMT, CFHR3, RPL8, and STMN1 all exceed a 2-fold change." (PMID 39176099, 2024). "Targeting STMN1 and PKM2 also shows promise in reducing cell growth, metastasis, and increasing tumor cell apoptosis." (PMID 38840205, 2024). "In this study, we further explored the relationship among STMN1, HMGA1, microtubule stability and tumor metastasis." (PMID 38385074, 2024). "Next, we evaluated the role of STMN1 and CRMP2, two major tubulin and mitosis regulators, in mediating the anti-tumor effects of CITs in MPM cells." (PMID 37305581, 2023). "The mRNA expression levels of STMN1, CLSPN, MDK, RNFT2, PRR11, and RNF157 were significantly increased in HCC tumor tissue; on the contrary, GHR was significantly decreased compared with normal tissues." (PMID 37542549, 2023). "Differential analysis showed that proliferation and antigen presentation genes, such as STMN1 and HLA‐DRA, were slightly up‐regulated in tumour cells, whereas differentiation molecules, such as KRT13, HOPX and CD24, were highly expressed in normal cells." (PMID 35608199, 2022). "Remarkably, the significant differences in STMN1 expression levels were found between PVTT and regular tumor tissues, as well as between PVTT and para-tumor tissues." (PMID 35210426, 2022). "We found that the STMN1 expression was significantly correlated with FIGO staging and tumor differentiation (P < 0.05)." (PMID 35186166, 2022). "We found that high expression of STMN1 was related to the age, weight, AFP level, tumor status, pathological stage, and histological grade of HCC patients." (PMID 36127700, 2022). "Subsequent studies displayed that circβ-catenin sponged to miR-223 to regulate STMN1 expression in GBC cells, which affected tumor progression." (PMID 34489401, 2021).
tumor (continued). "We then tested the expression pattern of FoxM1 and STMN1 in 18 cancer cell lines derived from LIHC, GC and CRC, and found a significantly positive correlation between FoxM1 and STMN1 in tumor cells." (PMID 33526768, 2021). "Thus, STMN1 could be used as a target and a marker for the prognosis of tumor treatment." (PMID 34107874, 2021). "Our qRT-PCR analysis demonstrated that STMN1 and ZNF292 were overexpressed in tumor samples, while PRKACB expression was higher in paracancerous samples." (PMID 33201835, 2020). "Consistent with our qRT-PCR results, ZNF292 and STMN1 staining were higher in tumor samples, while staining of PRKACB was lower in tumor." (PMID 33201835, 2020). "For instance, we found the microtubule-interacting protein stathmin (STMN1) and myristoylated alanine-rich protein kinase C substrate (MARCS) to be increased at the tumor periphery in most of the analyzed specimens." (PMID 29363612, 2018). "IHC was used to detect the protein expression levels of BRAC1, STMN1, MAPT and TUBB3 in cancer tissues and adjacent non-tumor tissues." (PMID 29113350, 2017). "In contrast, the protein and mRNA expression levels of STMN1 and TUBB3 in the cancer tissues were significant higher than that in the adjacent non-tumor tissues (p≤0.001)." (PMID 29113350, 2017). "Our results further indicate that THR down-regulates STMN1 expression and show that its expression is negatively correlated with that of STMN1 in HCC, supporting the role of THR as a tumor suppressor." (PMID 27934948, 2016). "Among those, we identified MCM5, STMN1, RCL1 and C9ORF114, proteins that reflect the high proliferation rate of these tumours." (PMID 26725330, 2016). "To better investigate the role which human PIWIL1 protein plays in tumor cells, we performed a bacterial two-hybrid screen using PIWIL1 as the bait and detected STMN1 as a PIWIL1-interacting protein." (PMID 26317901, 2015). "To further investigate the signaling pathway through which PIWIL1 regulates in tumor cells, we performed a bacterial two-hybrid assay using PIWIL1 as the bait and identified STMN1 as a target-protein." (PMID 26317901, 2015). "The proteomic clusters included tumor upregulated (PRDX3, APOA1, CLIC1) and downregulated (NFM, NDUS1, MDHC, ALDOC, STMN1, PEBP1, DDAH1, CN37) proteins." (PMID 25050814, 2014). "Additionally, dual immunofluorescence staining demonstrated co-expression of STMN1 and the NE marker Chromogranin A (CHGA) in NEPC cells scattered within an AdPC tumor exhibiting NE differentiation." (PMID 39776361, 2025). "Notably, the tumor progression in nude mice injected with PTX/si@MPDA-PEG was significantly inhibited, which can be attributed to the suppression of STMN1 expression, thereby enhancing chemosensitivity to PTX." (PMID 41361792, 2025). "Additionally, these cells exhibit specific upregulation of CEP55, PBK, BIRC5, STMN1, MT2 A, and CKS1B, all of which are related to tumor inflammatory responses." (PMID 40524208, 2025). "While accurately discerning differences in gene expression between liver normal and tumor tissues might be challenging, preliminary findings revealed elevated expressions of G6PD, STMN1, and PML in HCC tissues in comparison to normal liver tissues." (PMID 38317842, 2024). "In this dataset, all the 7-gene candidates exhibited a significant increase of mRNA expression in the metastasis group relative to localised tumours, with RUVBL1 exhibiting near statistical significance (U2AF2 P = 0.0106, RUVBL1 P = 0.051, HDGF P < 0.0001, FABP4 P = 0.0005, and STMN1 P = 0.032)." (PMID 39402324, 2024). "In the CPTAC database, the results showed that STMN1 total protein in LUAD tumor tissues was significantly higher than that in nontumor tissues." (PMID 38385074, 2024).
tumor (continued). "STMN1 expression significantly correlated with FIGO staging and tumor differentiation (P < 0.05)." (PMID 35186166, 2022). "We also established STMN1-overexpressed cell lines and performed in vivo experiments, but there was no obvious change in tumor weight and tumor volume compared with the control group." (PMID 33526768, 2021). "Interestingly, STMN1 and ANGPT2 were significantly positively correlated with tumor purity, whereas RAP1A, FLT3, HSPA8, and PGF were all significantly negatively correlated with tumor purity." (PMID 34178637, 2021). "We examined tumor cell lysates prepared from 3 patient-derived xenograft (PDX) tumors expressing high levels of p27 by immunoblot analysis, using antibodies against vimentin, snail-2, N-cadherin, β-catenin and STMN1." (PMID 30992462, 2019). "In addition, many studies have reported that hsa-miR-30a-5p is a tumor suppressor in GC, and recent studies have shown that CCNA2, MYBL2, DTL, and STMN1 are regulated by hsa-miR-30a-5p." (PMID 29912172, 2018). "The mean level of STMN1 mRNA expression was significantly higher in tumor samples than that in the non-cancerous counterparts (p = 0.040)." (PMID 22470493, 2012). "Moreover, ongoing studies target the identified genes (ENO1, STMN1, PKM, CDK1), with therapies like enolase 1 depletion demonstrating efficacy across various tumor types by inhibiting glycolysis, growth, proliferation, migration, metastasis, and sensitizing tumors to chemotherapy and radiotherapy." (PMID 38840205, 2024). "Furthermore, NEPC cells scattered in an AdPC tumor with neuroendocrine differentiation also displayed high STMN1 expression, as indicated by dual immunofluorescence staining for the NE marker Chromogranin A (CHGA) and STMN1." (PMID 39711570, 2024). "Finally, functional analysis of STMN1 was not performed using RNAi in tumor-bearing mouse models because animal experiments have reported that STMN1 suppression by RNAi inhibited the metastatic potential in an orthotopic NB mouse model." (PMID 37760452, 2023). "In addition, STMN1 was highly expressed in all tumor tissues from ten patients when compared to their matched non-tumor tissues collected from TCGA." (PMID 35210426, 2022). "Here, pan-cancer analysis provides strong hints between STMN1 and EMT, and in vitro experiments confirmed that STMN1 inhibition can increase the stability of microtubules and decrease the activity of adhesion spot kinase, thereby inhibiting the occurrence of EMT and affecting tumor metastasis." (PMID 35210426, 2022). "Furthermore, silencing STMN1 reversed the effects of circST6GALNAC6 on EMT and tumour metastasis." (PMID 33568625, 2021). "A combined analysis of scRNA-seq and spatial transcriptomics revealed an abundance of STMN1+ cECs and MYF5+ MSCs at the tumor invasion front in mono-immunotherapy non-responders." (PMID 40107247, 2025). "In the GEPIA database, the results illustrated that STMN1 was highly expressed in LUAD and LUSC tumor tissues compared with nontumor tissues." (PMID 38385074, 2024). "In this study, STMN1 mRNA was also found to be significantly more highly expressed in 21 LUAD and 13 LUSC tumor tissues than in matched adjacent nontumor tissues." (PMID 38385074, 2024). "This T3-mediated suppression of STMN1 supports the theory that T3 plays an inhibitory role in HCC tumor growth, and suggests that the lack of normal THR function leads to elevated STMN1 expression and malignant growth." (PMID 27934948, 2016). "Though the positive correlation between high STMN1 expression and poor prognosis of GC and CRC patients is not as apparently as that in LIHC, there is a trend that GC or CRC patients bearing highly STMN1-expressed tumor have poor prognosis." (PMID 33526768, 2021).
tumor (continued). "In addition, STMN1, MET, and HGF were expressed at similar levels in primary PCa tissues and mCRPC lesions in bone, adrenal gland, lung, lymph node, peritoneum, and bladder, inferring that the levels of STMN1, MET, and HGF expression were independent of any observed tumor heterogeneity between men." (PMID 40723207, 2025).
cancer (151 papers, 2006 to 2026). A tumor composed of atypical neoplastic, often pleomorphic cells that invade other tissues. "STMN1 is essential for regulating microtubule motility and is implicated in cancer cell division and proliferation." (PMID 38114977, 2023). "It is also reported that overexpressing STMN1 was closely associated with vascular invasion, drug resistance and shorter survival time in cancer patients in vivo." (PMID 37754250, 2023). "MiR-770 is transferred by exosomes and causes chemosensitivity in cancer cells via the downregulation of stathmin 1 (STMN1) and suppressed cell invasion and migration by modification of the epithelial–mesenchymal transition (EMT) pathway." (PMID 37153758, 2023). "STMN1 was also a high-risk factor in many malignancies according to the univariate cox analysis across 33 cancer types." (PMID 35210426, 2022). "STMN1 is a hallmark gene for cancer prediction, mainly due to its active involvement in cell proliferation, cell cycle and cancer progression." (PMID 35409358, 2022). "According to the ROC diagnostic curve, STMN1 expression was able to distinguish cancers from normal tissues with high accuracy (AUC = 0.972)." (PMID 36127700, 2022). "High STMN1 expression has been associated with poor prognosis in many different tissue-derived cancer types such as hepatoma, cholangiocarcinoma." (PMID 37529254, 2022). "Specifically, STMN1 was positively correlated with mesenchymal markers while negatively associated with epithelial markers across 33 cancer types, including HCC." (PMID 35210426, 2022). "STMN1 regulated cancer-associated fibroblast (CAF) features through HSC by triggering the HGF/MET signaling pathway." (PMID 34178637, 2021). "The data indicated that high levels of FoxM1 and STMN1 are closely associated with poor prognosis in cancers, thus shedding light on the prognostic value of combined utilization of FoxM1 and STMN1." (PMID 33526768, 2021). "And more importantly, though the high level of STMN1 frequently indicates poor prognosis in cancer patients, the underlying mechanism for high level of STMN1 in cancers is still elusive." (PMID 33526768, 2021). "In this study, we queried the HCC cancer genomics data via the cBioPortal website to determine the genetic alterations (mutations and copy number variations) of the STMN1 gene in HCC." (PMID 33922244, 2021). "Some studies suggested that the silencing of the Stathmin-1-encoding gene can inhibit cancer cell migration and metastatic potential." (PMID 32823874, 2020). "Being a hallmark in cancer prediction, the STMN1 gene plays key roles in cell cycle regulation, proliferation, and progression of cancer." (PMID 33233533, 2020). "Elevated expression of STMN1 in cancer is associated with the proliferation and matastasis of a variety of cancer cells." (PMID 27349455, 2016). "Elevated expression of STMN1 in cancer is invariably associated with the proliferation and matastasis of cells." (PMID 27349455, 2016). "For this reason, disturbances in stathmin 1 expression have been associated with several types of cancer." (PMID 22558331, 2012). "The expression of STMN1 in cancer cells has been associated with their proliferation and metastasis." (PMID 23071542, 2012). "However, in addition to primarily epithelial-derived cancer cells, solid tumors contain numerous other cell types that express STMN1, including cancer-associated fibroblasts (CAFs), endothelial, and immune cells." (PMID 40723207, 2025). "The overexpression of miR-34a was associated with a decreased expression of STMN1 and elevated expression of β3-Tubulin, which led to the disruption of the microtubule network, decreased cancer cell proliferation, cell cycle arrest in the G0/G1 phase, and increased apoptosis." (PMID 37165308, 2023). "Stathmin 1 depletion is known to cause cell cycle arrest and apoptosis in various cancer cells." (PMID 32410663, 2020). "Some evidence associates the overexpression of the STMN1 to the cancer progression." (PMID 28686225, 2017).